TIAL1 (TIA1 cytotoxic granule associated RNA binding protein like 1)
Description:
RNA-binding protein involved in alternative pre-RNA splicing and in cytoplasmic stress granules formation. Shows a preference for uridine-rich RNAs. Activates splicing of alternative exons with weak 5' splice sites followed by a U-rich stretch on its own pre-mRNA and on TIA1 mRNA (By similarity). Promotes the inclusion of TIA1 exon 5 to give rise to the long isoform (isoform a) of TIA1. Acts downstream of the stress-induced phosphorylation of EIF2S1/EIF2A to promote the recruitment of untranslated mRNAs to cytoplasmic stress granules (SG). Possesses nucleolytic activity against cytotoxic lymphocyte target cells. May be involved in apoptosis.
Synonyms: TIAR; TCBP
Tractability: PROTAC: ubiquitination databases record sites on it; its protein half-life has been measured.
Gene: Protein-coding gene on chromosome 10 (119,571,802 to 119,597,029, reverse strand). Ensembl gene ENSG00000151923.
Subcellular location: Nucleus; Cytoplasm; Cytolytic granule; Cytoplasm, Stress granule
Subcellular location (Human Protein Atlas): Nucleoplasm; Cytosol
Pathways (Reactome):
Signal Transduction: FGFR2 alternative splicing
Gene Ontology:
Molecular function: mRNA 3'-UTR binding; protein binding; protein-RNA adaptor activity; RNA binding; DNA binding; nucleic acid binding
Biological process: negative regulation of cell population proliferation; positive regulation of hippo signaling; positive regulation of miRNA-mediated gene silencing; apoptotic process; defense response; regulation of alternative mRNA splicing, via spliceosome; regulation of transcription by RNA polymerase II; regulation of cell population proliferation
Cellular component: cytolytic granule; cytosol; nucleoplasm; nucleus; cytoplasm; cytoplasmic stress granule; lysosome
Genetic constraint (gnomAD): Loss-of-function variants: 6 observed, 55.68 expected, observed/expected ratio (o/e) 0.11, 90% interval 0.058 to 0.21. The upper end of that interval is the gene's LOEUF score, 0.21, which puts it in group 1 of 6, group 1 being the genes least tolerant of losing a copy. Missense variants: 200 observed, 440.23 expected, observed/expected ratio (o/e) 0.45, 90% interval 0.4 to 0.51. Synonymous variants: 131 observed, 139.2 expected, observed/expected ratio (o/e) 0.94, 90% interval 0.82 to 1.09.
Homologues: Orthologues: chimpanzee TIAL1 (100% identical), dog TIAL1 (100% identical), macaque TIAL1 (100% identical), mouse Tial1 (99% identical), rat Tial1 (99% identical), pig TIAL1 (97% identical), tropical clawed frog tial1 (92% identical), rabbit TIAL1 (87% identical). Paralogues in human: TIA1 (79% identical), RBM39 (19% identical), RBM19 (18% identical), RBM4 (18% identical), HNRNPA2B1 (18% identical), HNRNPA3 (18% identical), RBM4B (18% identical), RBM47 (18% identical), NUCLEOLIN (18% identical), TRNAU1AP (17% identical), HNRNPA0 (17% identical), HNRNPD (17% identical), and 24 more.
Diseases named in the same sentence as TIAL1 in open-access papers:
TIAL1 is named in the same sentence as 46 diseases in open-access papers, as found by Europe PMC text mining. Sharing a sentence is not in itself a finding about the gene and the disease. The quoted sentences say what the papers report.
glioma (5 papers, 2022 to 2025). A benign or malignant brain and spinal cord tumor that arises from glial cells (astrocytes, oligodendrocytes, ependymal cells). "Similarly, the lncRNA PHAROH regulates Myc translation in hepatocellular carcinoma by sequestering TIAL1, and the lncRNA LOXL1-AS1 interacts with TIAR to modulate vasculogenic mimicry in glioma through the regulation of the miR-374b-5p/MMP14 axis." (PMID 35887183, 2022).
breast carcinoma (3 papers, 2020 to 2022). "If TIAL1 has the same effect on BRCA1 protein expression in breast cancer, it is plausible that SNPs that increase TIAL1 expression also increase breast cancer risk, as is the case with rs3009879." (PMID 32714364, 2020). "For example, TIAL1 was top significant in both univariate and LASSO Cox regression analysis and was found to be a prognostic risk factor for breast cancer." (PMID 35719389, 2022). "We report here putative breast cancer risk SNPs predicted to functionally target GABPB1-AS1 lncRNA, and associating with its expression, as well as SNPs in two genes, CPEB4 and TIAL1, hosting ultraconserved regions, uc.184 and uc.313, respectively." (PMID 32714364, 2020). "In addition, putative breast cancer risk associated SNPs (p < 1 × 10–5) in the region of two T-UCRs, uc.184 and uc.313, located in protein coding genes CPEB4 and TIAL1, respectively, targeted these genes in INQUISIT and in eQTL analysis." (PMID 32714364, 2020).
ulcerative colitis (2 papers, 2021 to 2022). An inflammatory bowel disease involving the mucosal surface of the large intestine and rectum. "In addition, two of the top dysregulated ALP genes, TIAL1 and CALCOCO2, have been implicated as key factors in ulcerative colitis- and Crohn’s disease-related inflammation, respectively." (PMID 34446734, 2021).
Arthritis (1 paper, 2021). Inflammation of a joint. "TIAL1-deficient mice develop arthritis and elevated TNF expression." (PMID 34578166, 2021).
cholesteatoma (1 paper, 2023). A pathologic process characterized by the proliferation of keratinizing squamous epithelium resulting in the accumulation of keratin and cells in the middle ear and/or mastoid. "However, whether TIAL1 and MUC12 are involved in the pathogenesis of cholesteatoma requires further investigation." (PMID 37609036, 2023).
chronic myeloid leukemia (1 paper, 2020). "TIAL1 is a negative regulator of BRCA1: it is shown to block translation, and at least in chronic myeloid leukemia cells, reduce the protein expression of BRCA1 which leads to aneuploidy, spindle toxin resistance, and genomic instability." (PMID 32714364, 2020).
lymphopenia (1 paper, 2022). Reduction in the number of lymphocytes. "Altogether, our results reveal that TIA1 and TIAL1 play essential, but redundant, roles during the development of B cells, and that peripheral lymphopenia is due to a severe block at the pro-B cell stage." (PMID 36543128, 2022).
melanoma (1 paper, 2024). A malignant, usually aggressive tumor composed of atypical, neoplastic melanocytes. "Although in melanoma the presence of the retinoblastoma binding (RB) mRNA Rbfox2 in SGs was associated with progression and metastasis, the presence of TIA1, G3BP1, and TIAL1 in melanoma-derived SGs has not been reported, so new experimental approaches would be needed." (PMID 39594467, 2024).
cancer (16 papers, 2013 to 2025). A tumor composed of atypical neoplastic, often pleomorphic cells that invade other tissues. "Twelve SNPs were located within gene regions, corresponding to nine genes, among which PTPN13 and TIAL1 are associated with cancer and immune function (Table A6)." (PMID 40427243, 2025). "Here, we show that TIA1 and TIAL1 bind to the same RNA binding sites and act redundantly over their RNA targets, as previously shown in different cancer cell lines." (PMID 37474714, 2023). "TIA1 and TIAL1 were first described in cancer-infiltrating cytotoxic T cells." (PMID 37474714, 2023). "Notably, the cancer-prevention effect was achieved by repression of the PI3K-Akt-mTORC1 activity through TIAL1-mediated translational suppression." (PMID 25853883, 2015). "Several RBPs exhibited widespread activities in various cell types and cancer types, such as HNRNPH3, HNRNPH1 and TIAL1." (PMID 36681772, 2023).
infection (10 papers, 2011 to 2023). The state of being infected such as from the introduction of a foreign agent such as serum, vaccine, antigenic substance or organism. "An example can be seen in the circRNA produced by TIAL1 whose abundance increases after infection, whereas its linear transcript is down-regulated." (PMID 32764824, 2020).
tumor (10 papers, 2015 to 2024). "A previous study showed that knockdown of TIAL1 results in increased cell proliferation, tumor growth, and invasion, Moreover, the TIAL1 protein was shown to be downregulated in many tumors of epithelial origin, including skin, breast, and colon." (PMID 37609036, 2023).
TIAL1 also shares sentences with these, for which no sentence is quoted: hepatocellular carcinoma (4 papers); ZIKV infection (4); viral infections (3); asthma (2); colorectal cancer (2); leukemia (2); pulmonary sarcoidosis (2); amoebiasis (1); Autoimmunity (1); B cell lymphomas (1); brain ischemia (1); cervical carcinoma (1); chronic obstructive pulmonary disease (1); Cirrhosis (1); colon adenocarcinoma (1); Crohn disease (1); cutaneous squamous cell carcinoma (1); dyslipidemia (1); endometrial cancer (1); esophageal carcinoma (1); gastric cancer (1); glioblastoma (1); hepatitis C (1); idiopathic interstitial pneumonia (1); laryngeal squamous cell carcinoma (1); liver fibrosis (1); lung carcinoma (1); lung squamous cell carcinoma (1); neuroblastoma (1); Obesity (1).
A further 5 diseases each share a sentence with TIAL1 in 1 paper.